Y_RNA (Y RNA )
Gene: Miscellaneous RNA gene on chromosome 15 (30,355,436 to 30,355,540, forward strand). Ensembl gene ENSG00000238783.
Homologues: Orthologues: chimpanzee Y_RNA (98% identical), macaque Y_RNA (97% identical). Paralogues in human: Y_RNA (100% identical), Y_RNA (85% identical), RNY3 (84% identical), Y_RNA (84% identical), RNY3P1 (83% identical), Y_RNA (83% identical), Y_RNA (82% identical), Y_RNA (81% identical), Y_RNA (80% identical), RNY3P11 (79% identical), RNY3P16 (79% identical), Y_RNA (79% identical), and 93 more.